RNU6-270P (RNA, U6 small nuclear 270, pseudogene)
Gene: Small nuclear RNA gene on chromosome 10 (28,760,699 to 28,760,803, reverse strand). Ensembl gene ENSG00000201001.
Homologues: Orthologues: chimpanzee U6 (99% identical), macaque U6 (93% identical), rat U6 (80% identical). Paralogues in human: RNU6-11P (88% identical), RNU6-1287P (88% identical), RNU6-1309P (88% identical), RNU6-242P (88% identical), RNU6-24P (88% identical), RNU6-37P (88% identical), RNU6-726P (88% identical), RNU6-727P (88% identical), RNU6-1083P (87% identical), RNU6-1091P (87% identical), RNU6-1243P (87% identical), RNU6-12P (87% identical), and 1286 more.